EGFR (epidermal growth factor receptor)
Diseases named in the same sentence as EGFR in open-access papers (continued):
Sharing a sentence is not in itself a finding about the gene and the disease.
ovarian tumors (continued). "In addition to EGFR, when we screened the RTKs commonly involved in ovarian tumor progression, we found that several RTKs with moderate expression levels can also be regulated by thyrostimulin-TSHR signaling in NIH:OVCAR 3 cells." (PMID 27273257, 2016). "Since we observed suppression of ovarian tumors by oral administration of PEITC, we hypothesized that growth inhibitory effects of PEITC in ovarian tumors in vivo were through inhibition of EGFR-AKT." (PMID 22952709, 2012). "EGFR-AKT pathway is constitutively activated in majority of ovarian tumors." (PMID 22952709, 2012). "For example, treatment of ovarian tumors with anti-EGFR or PDGFR agents had little response." (PMID 21962244, 2011). "In our system, loss or reduction of EphA2 through interaction with YSA-functionalized nanogels may provide an enhanced effect over delivery of EGFR siRNA alone leading to a dual-targeting strategy for chemosensitization of ovarian tumors." (PMID 20064265, 2010). "When EGFR shRNA sequences were applied to pT7/shRNA DNA fragments, a single systemic injection could suppress the expression of EGFR gene in the tumor sites for more than two weeks, substantially inhibiting the ovarian tumor growth." (PMID 30816180, 2019). "Furthermore, activation of EGFR has been shown in ~30% of ovarian tumors." (PMID 26351843, 2015). "Epidermal growth factor receptor (EGFR)-targeted polymeric nanoparticles (NPs) loaded with lonidamine and paclitaxel showed increased antitumor activity in human breast and ovarian tumor cells." (PMID 33918086, 2021). "A well-established anti-EGFR PIC was used to target and deliver a photosensitizing agent, in this case, BPD, to 3D ovarian tumors." (PMID 32231055, 2020). "For example, in ovarian tumors, AXL dimerizes with MET, EGFR, and HER2, leading to sustained ERK activation." (PMID 32245042, 2020). "The expression pattern of EGFR, HER-2, HER-3 and HER-4 was determined in 60 FIGO stage III and IV ovarian tumour specimens." (PMID 29731973, 2018). "Reported positive staining in ovarian tumor tissue varied widely, ranging from 9% to 88%; contributing reasons could be differences in antibodies, tissue processing, staining techniques, and patient populations, as well as methodological differences in scoring of the EGFR tissue staining." (PMID 28740577, 2017). "Epidermal growth factor receptor (EGFR), hepatocyte growth factor receptor (Met) and cellular Src kinase (c-Src) are crucial kinases implied in ovarian tumor growth, survival, invasion and resistance to carboplatin." (PMID 28446239, 2017). "The epithelial phenotype of ovarian tumors facilitates the activation of PI3K/AKT and EGFR pathways for tumor growth and survival and also for the invasion into local tissues via collective cell movement." (PMID 26871283, 2016). "Growth inhibitory effects of PEITC were mediated by inhibition of EGFR and AKT, which are known to be overexpressed in ovarian tumors." (PMID 22952709, 2012). "In contrast, overexpression/amplification of certain oncogenes like C-MYC, RAS, AKT, EGFR (ErbB1 or HER1), HER2/neu (ErbB2), CSF1 C-MYC, etc., is also well known in ovarian tumors." (PMID 20034397, 2009). "NCX-4040 can resensitize and potentiate the anticancer effect of cisplatin through downregulation of EGFR and STAT3 signaling in cisplatin-resistant human ovarian tumor xenografts in mice." (PMID 18302761, 2008). "HS 6-O-sulfation levels, determined by the expression of 6OSTs, have been reported as critical for the activation of epidermal growth factor receptor (EGFR) by heparin biding-EGF (HBEGF), and the consequent increase in the expression of angiogenic cytokines on ovarian tumour cells." (PMID 33494442, 2021). "Interestingly, low-dose anti-EGFR photoimmunotherapy (PIT), a targeted photochemical modality, was found to be equally effective in ovarian tumors grown under flow and static conditions." (PMID 32231055, 2020).
ovarian tumors (continued). "Receptor EGFR, ERBB2, MET, and AXL were strongly co-activated in most primary ovarian tumors." (PMID 21962244, 2011). "While screening for this phase II trial included EGFR positivity in the ovarian tumor as determined by IHC, no responses to therapy were observed." (PMID 20037743, 2010). "This was not due to amplification of the EGFR gene in any of the 25 ovarian tumours studied (including 6 which showed high expression of EGFR in IH)." (PMID 1457340, 1992). "We initially measured the mRNA expression levels of the HER family in ovarian tumor tissues, which include EGFR, HER2, HER3, and HER4, and found a significant negative correlation between the expression levels of HER3 and levels of CYLD, but not levels of other HER family members." (PMID 40012003, 2025). "However, unlike some other EGFR-positive solid tumors, treatment of ovarian tumors with anti-EGFR agents has induced minimal response." (PMID 20037743, 2010). "Importantly, our studies agree with previous reports that demonstrate that EGFR is a major regulator of TnT formation, and we have further shown that ERK and RSK are effectors responsible for formation of structures consistent with TnTs that connect ovarian tumor cells." (PMID 33450985, 2021).
oligodendroglioma (52 papers, 1997 to 2026). A well-differentiated (WHO grade II), diffusely infiltrating neuroglial tumor, typically located in the cerebral hemispheres. "Another EGFR gene variant, rs4947979, correlated with lower EGFR concentration in oligodendroglioma cases (P = 0.050)." (PMID 26906551, 2016). "The amplification and mutation of EGFR has been detected in 40%-50% of GBMs and oligodendrogliomas, EGFRvIII, which is a constitutively active EGFR mutant, can be detected in 12%-16% of GBM by IHC." (PMID 25644759, 2015). "Additionally, strong EGFR expression was associated with reduced survival in WHO grade II oligodendrogliomas, but was a favorable marker for survival in WHO grade III anaplastic oligodendrogliomas." (PMID 38595969, 2024). "Overexpression of EGFR in 100% of oligodendrogliomas with the G-allele may be related to differential activity of Ras/MAPK pathways and point to possible dependence on RTK activation in these tumors." (PMID 27282637, 2016). "Another model of oligodendroglioma is the GEMM expressing an activated allele of EGFR (v-erbB)." (PMID 25008045, 2014). "Loss of chromosomal regions on 1p and 19q is characteristic of oligodendrogliomas, but there is also evidence for another subset of oligodendrogliomas that have amplification of EGFR oncogene, loss of heterozygosity on chromosome 10 and homozygous deletion of the CDKN2A tumor suppressor gene." (PMID 18173856, 2008). "Oligodendroglioma with EGFR Amp tended to have larger maximal tumor diameter (5.83 ± 1.81 vs. 4.30 ± 2.13)." (PMID 38595969, 2024). "Meanwhile, owing to insufficient endpoints, we were unable to determine the role of EGFR Amp in predicting oligodendroglioma patients’ OS." (PMID 38595969, 2024). "All grades of oligodendrogliomas overexpress EGFR, and only high-grade tumors are found to have ink4a/arf deletion." (PMID 37705736, 2023). "IDH-wildtype GBM demonstrates alterations in epidermal growth factor receptor (EGFR), and similar to oligodendrogliomas, exhibit TERT promoter mutations." (PMID 37274223, 2023). "For instance, its positive connection with the epidermal growth factor receptor (EGFR) in high-grade oligodendroglioma suggests diverse roles." (PMID 37835380, 2023). "More narrowing bioinformatic pipelines can be used to also assess the co-deletion 1p-19q, a prerequisite for oligodendroglioma diagnosis, or the therapeutically targetable Epidermal Growth Factor Receptor (EGFR) amplifications." (PMID 35806153, 2022). "Our findings mirror this classification, with 1p/19q deletions mostly confined to oligodendrogliomas with and IDH1 mutation or G-CIMP signature, and EGFR amplification observed mostly in IDH1 wild type GII/III s and GBMs." (PMID 24614622, 2014). "Using fluorescent in situ hybridization and whole genome sequencing, we studied a xenografted human oligodendroglioma where the co-amplification of the EGFR and MYC loci was present in the form of dmins at early passages and of an hsr at later passages." (PMID 25378339, 2014). "In oligodendroglioma, EGFR-amplified tumor had larger maximal tumor diameter." (PMID 38595969, 2024). "Although few articles reported similar finding, it could be explained by higher histological grade in EGFR-amplified oligodendroglioma in our study." (PMID 38595969, 2024). "This study confirms that combination of gefitinib with fractionated irradiation could be a potent therapeutic strategy for anaplastic oligodendrogliomas harboring EGFR abnormalities but this treatment seems mainly beneficial for “EGFR-addictive” tumors." (PMID 23874590, 2013). "Of the six classic and five neural oligodenrogliomas, none of the neural and only two of the classic oligodendrogliomas had high patient age (>70), chr10 loss, and/or EGFR amplification." (PMID 20838435, 2010). "Interestingly, one of the two low-grade oligodendrogliomas clustered with the EGFR group (ODG.22) and did in fact harbor high-level EGFR amplification." (PMID 19915670, 2009).
oligodendroglioma (continued). "Interestingly, overexpression of EGFR in transgenic mice has been shown to be involved in tumour progression of oligodendroglioma." (PMID 14676814, 2003). "Besides, oligodendroglioma with EGFR Amp was more likely to manifest as higher histological grade." (PMID 38595969, 2024). "By contrast, SSTR2 expression was associated with IDH1 mutation (P = 0.007), oligodendroglioma component (P = 0.010), lower grade (P = 0.005), absence of EGFR amplification (P = 0.021), and longer progression-free survival (HR 0.161, CI 0.037 to 0.704, P = 0.015)." (PMID 25977882, 2015). "Using fluorescent in situ hybridization (FISH) and whole genome sequencing approaches, we analysed at nucleotide resolution the organization of co-amplified sequences from the EGFR and MYC loci at successive passages of a xenografted human oligodendroglioma." (PMID 25378339, 2014). "Remarkably, NG2+ OPC-like cells isolated from human oligodendrogliomas also exhibit defective ACD, leading to an overproduction of daughter cells that inherit both NG2 and EGFR." (PMID 23771628, 2014). "In the xenografted human oligodendroglioma ODA14, the EGFR (7p11) and the MYC (8q24) loci were co-amplified and the amplified sequences resided on dmins at passage 2 (ODA14p2) and on an hsr at passage 4 (ODA14p4)." (PMID 25378339, 2014). "In particular, we focused on three models of anaplastic oligodendrogliomas (TCG2, TCG3 and TCG4) that harbored the highest phospho-EGFR expression levels." (PMID 23874590, 2013). "In addition to these genomic alterations, increased EGFR and PDGF/PDGFR expression is frequently observed in oligodendrogliomas." (PMID 25008045, 2014). "Unfortunately, this study demonstrates that the basal overexpression of phospho-EGFR, along with the overexpression of phospho-AKT and phospho-MEK1, surrogate markers of the EGFR- pathways activation in tumors, are not sufficient to predict this “EGFR-addiction” in oligodendrogliomas." (PMID 23874590, 2013).
chronic obstructive pulmonary disease (51 papers, 2013 to 2026). A chronic and progressive lung disorder characterized by the loss of elasticity of the bronchial tree and the air sacs, destruction of the air sacs wall, thickening of the bronchial wall, and mucous accumulation in the bronchial tree. "Based on the FDA Adverse Events Reporting System (FAERS), a public database that contains nearly 17 million (adverse event) AE reports, EGFR TKIs have been associated with HF and cardiac arrhythmias such as atrial fibrillation and QT prolongation." (PMID 36818331, 2023). "Second, smokers frequently present with comorbid pulmonary pathologies such as emphysema, chronic obstructive pulmonary disease, inflammation, and fibrosis, which can interfere with imaging biomarkers associated with EGFR mutations and further reduce model accuracy." (PMID 41415549, 2025). "The most frequently reported cardiac arrhythmia associated with EGFR-TKIs is QT prolongation." (PMID 36818331, 2023). "In a retrospective study based on the world health organization (WHO) pharmacovigilance database VigiBase, among 98,765 adverse reactions reported with NSCLC-targeted therapies including EGFR-TKIs, 1,783 (1.8%) were cardiac arrhythmias." (PMID 36818331, 2023). "We focused on C3 group which is characterized by low immune infiltration (cold tumor) and wild-type EGFR, posing a significant challenge for treatment of LUAD." (PMID 32855362, 2020). "Th2 cytokines also amplify the mucus-inducing EGFR signaling, which is highly activated in cystic fibrosis, chronic obstructive pulmonary disease (COPD) and asthma." (PMID 32269574, 2020). "Aberrant activity of a disintegrin and metalloprotease 17 (ADAM17), also known as TACE, and epidermal growth factor receptor (EGFR) has been suggested to contribute to chronic obstructive pulmonary disease (COPD) development and progression." (PMID 27561911, 2016). "More specifically, in a review by Stolarczyke and Scholte examining chronic obstructive pulmonary disease and cystic fibrosis, extensive evidence was found linking hyperactivity of the EGFR/ADAM17 signaling axis to ADAM17-cleavage of amphiregulin, an EGFR ligand." (PMID 34745017, 2021). "*ECOGPS: Eastern cooperative oncology group performance status, COPD: Chronic obstructive pulmonary disease, EGFR: Epidermal growth factor receptor, ALK: Anaplastic lymphoma kinase." (PMID 39583517, 2024). "However, HIF-1α is abundant in chronic obstructive pulmonary disease, which may interact with cytokines through epidermal growth factor receptor (EGFR)/phosphoinositide 3-kinase (PI3K)/protein kinase B (AKT) pathway and further up-regulate HIF-1α self." (PMID 36724056, 2023). "In the airway of patients with chronic obstructive pulmonary disease (COPD), quercetin restores nuclear Foxo3a and reduces chemokine expression partly by modulating epidermal growth factor receptor/PI3K/Akt activity to improve lung function." (PMID 33892727, 2021). "Besides controlling lung embryogenesis and morphogenesis, EGFR plays an essential function in lung homeostasis and airway remodeling that is reflected in different forms of chronic obstructive pulmonary disease (COPD), including acute asthma and fibrosis." (PMID 39966897, 2025). "We also noticed that the levels of lipid markers and LSRscore were not affected by age, smoking status, EGFR mutations, COPD (chronic obstructive pulmonary disease) and bronchiectasis, confirming the stability of lipid marker and LSRscore classification." (PMID 38467839, 2024). "In the subgroup with tissues available for EGFR testing (N = 332), gender, chronic obstructive pulmonary disease (COPD) status, smoking status, pathological subtype, and pathological T stage (pT) were significantly different between EGFRm patients and EGFR wild-type patients." (PMID 38347487, 2024).
chronic obstructive pulmonary disease (continued). "During chronic obstructive pulmonary disease progression, miR-132 overexpression targeted and inhibited SOCS5, thereby promoting EGFR protein expression and inflammatory cytokine production in human mononuclear cells." (PMID 38267898, 2024). "*PDL-1: Programmed cell death ligand-1, TPS: Tumor percentage score, ECOGPS: Eastern cooperative oncology group performance status, COPD: Chronic obstructive pulmonary disease, EGFR: Epidermal growth factor receptor, ALK: Anaplastic lymphoma kinase." (PMID 39583517, 2024). "A total of 379 targets related to BHC and 7391 targets related to COPD were obtained, including 313 potential targets of BHC in treating chronic obstructive pulmonary disease, with JUN, AKT1, TNF, IL6, EGFR, MAPK1, and MAPK14 as the core targets." (PMID 36523421, 2022). "Molecular Characterization of Chronic Obstructive Pulmonary Disease-Related NSCLC through WIF-1aberrant methylation and Alterations of EGFR Signaling." (PMID 27911280, 2017). "Goblet cell metaplasia and MUC5AC expression are increased under pathological conditions such as chronic rhinosinusitis or chronic obstructive pulmonary disease (COPD); in addition, cigarette smoke enhanced the pathological response, which was mainly mediated by the EGFR pathway." (PMID 38892239, 2024). "Although several clinicopathologic factors to predict the response to and survival on EGFR-TKI were recognized, its efficacy has not been confirmed for patients with underlying pulmonary disease, such as chronic obstructive pulmonary disease (COPD)." (PMID 31336878, 2019). "We then asked whether EGFR-YAP dependent unjamming was specific to IPF epithelia or if this axis was common among other chronic lung disease, such as chronic obstructive pulmonary disease (COPD)." (PMID 34315881, 2021).